TLE3 (TLE family member 3, transcriptional corepressor)
Description:
Transcriptional coregulator that binds to a number of transcription factors. Acts as a regulator of adipogenesis both by acting as a corepressor of Wnt signaling and coactivator for PPARG. Inhibits the transcriptional activation mediated by CTNNB1 and TCF family members in Wnt signaling. Promotes diffentiation of white adipocytes by acting as a coactivator for PPARG and preventing the association between PRDM16 and PPARG, thereby preventing browning of white adipocytes (By similarity).
Synonyms: ESG3; KIAA1547; ESG; HsT18976; GRG3
Tractability: PROTAC: UniProt records ubiquitination sites on it; ubiquitination databases record sites on it.
Gene: Protein-coding gene on chromosome 15 (70,047,790 to 70,098,176, reverse strand). Ensembl gene ENSG00000140332.
Subcellular location: Nucleus; Chromosome
Subcellular location (Human Protein Atlas): Nucleoplasm; Cytosol
Pathways (Reactome):
Signal Transduction: Deactivation of the beta-catenin transactivating complex; Estrogen-dependent gene expression; Formation of the beta-catenin:TCF transactivating complex; NOTCH1 Intracellular Domain Regulates Transcription; Repression of WNT target genes
Gene Ontology:
Molecular function: protein binding; transcription coactivator activity; transcription corepressor activity
Biological process: fat cell differentiation; negative regulation of canonical Wnt signaling pathway; white fat cell differentiation; animal organ morphogenesis; negative regulation of cold-induced thermogenesis; signal transduction; negative regulation of DNA-templated transcription; positive regulation of DNA-templated transcription; regulation of DNA-templated transcription
Cellular component: beta-catenin-TCF complex; chromatin; nucleoplasm; nucleus; chromosome; transcription regulator complex
Genetic constraint (gnomAD): Loss-of-function variants: 12 observed, 70.41 expected, observed/expected ratio (o/e) 0.17, 90% interval 0.11 to 0.28. The upper end of that interval is the gene's LOEUF score, 0.28, which puts it in group 1 of 6, group 1 being the genes least tolerant of losing a copy. Missense variants: 651 observed, 908.82 expected, observed/expected ratio (o/e) 0.72, 90% interval 0.67 to 0.76. Synonymous variants: 406 observed, 382.83 expected, observed/expected ratio (o/e) 1.06, 90% interval 0.98 to 1.15.
Homologues: Orthologues: chimpanzee TLE3 (100% identical), dog TLE3 (99% identical), macaque TLE3 (99% identical), rat Tle3 (99% identical), mouse Tle3 (99% identical), pig TLE3 (99% identical), guinea pig TLE3 (99% identical), rabbit TLE3 (98% identical), zebrafish tle3b (92% identical), zebrafish tle3a (90% identical), Drosophila melanogaster gro (63% identical). Paralogues in human: TLE4 (83% identical), TLE1 (80% identical), TLE2 (66% identical), TLE6 (19% identical), TLE7 (19% identical), TLE5 (16% identical).
Diseases named in the same sentence as TLE3 in open-access papers:
TLE3 is named in the same sentence as 64 diseases in open-access papers, as found by Europe PMC text mining. Sharing a sentence is not in itself a finding about the gene and the disease. The quoted sentences say what the papers report.
breast carcinoma (15 papers, 2009 to 2025). "In this study of breast cancer patients receiving adjuvant chemotherapy at two independent institutions, TLE3 staining was associated with improved disease-free survival in patients receiving a taxane-containing regimen as opposed to anthracycline without taxane." (PMID 19309506, 2009). "More recently, TLE3 was identified in a screen for genes causing estrogen independence in breast cancer cell lines and RNA levels further shown to be associated with progression-free survival in ER-expressing patients treated with tamoxifen as first-line treatment for metastatic disease." (PMID 19309506, 2009). "This study of IHC staining with TLE3 antibody in breast carcinoma and its association with outcome supports the hypothesis that increased TLE3 expression may predict those patients who will respond to taxane therapy." (PMID 19309506, 2009). "TLE3 is a full-length human TLE family member that plays an important role in breast cancer cell differentiation and proliferation." (PMID 38203206, 2023). "The expression levels of miR-3677 were reported to be negatively correlated with TLE3 expression in breast cancer tissue, suggesting that miR-3677 is involved in breast cancer cell proliferation and metastasis by suppressing TLE3 expression." (PMID 38203206, 2023). "Cox regression and Kaplan–Meier analysis suggested that TLE3 was a protective factor for breast cancer." (PMID 36451774, 2022). "A recent study has shown that miR-3677 can accelerate cell proliferation, migration, and invasion by targeting TLE3 in human breast cancer." (PMID 36451774, 2022). "The level of TLE3 expression was also found to be positively correlated with the sensitivity of breast cancer cells to tamoxifen treatment." (PMID 36438567, 2022). "TLE3-positive nuclear staining of breast cancer cells demonstrated a better survival rate when patients underwent systemic combination therapy with taxanes." (PMID 33802643, 2021). "TLE3 is deregulated in various cancers including hormone-driven breast cancer, colorectal cancer and prostate cancer." (PMID 31855178, 2019). "A recent study showed that TLE3 suppresses target genes of estrogen receptor alpha (ERα) by interacting with FOXA1 in breast cancer MCF-7 cells." (PMID 31569653, 2019). "Taken together, these results support the importance of TLE3 in the regulation of E2 target genes transcription, and its putative role in breast cancer biology." (PMID 25223786, 2014). "In human, TLE3 function has been explored in various cell lines, namely, adipocytes, prostate cancer cells, ovarian carcinoma cells and breast cancer cells." (PMID 25223786, 2014). "In breast cancer, the progression-free survival of patients with ERα+ tumors is positively correlated with TLE3 expression." (PMID 25223786, 2014). "We describe herein the nomination and validation of TLE3 as a novel biomarker of response to taxane therapy in breast cancer." (PMID 19309506, 2009). "We believe TLE3 should be studied in larger clinical trial populations to further assess its potential as a predictive marker for taxane therapy in breast cancer." (PMID 19309506, 2009). "TLE3 is one of the critical signatures we use to predict the prognosis of breast cancer." (PMID 39781342, 2025). "TLE3 binds FOXA1 to inhibit the expression of ER target genes in breast cancer cells, which may explain the influence of TLE3 on the sensitivity of tumor cells to tamoxifen treatment." (PMID 36438567, 2022). "The results showed that total protein expression of TLE3 was elevated in the primary tissues of breast cancer, clear cell RCC, lung adenocarcinoma, pancreatic adenocarcinoma, glioblastoma multiforme, hepatocellular carcinoma, ovarian cancer, and UCEC than in normal tissues." (PMID 36451774, 2022). "Moreover, survival data were analyzed using the Kaplan–Meier mapping tool, and a correlation was found between low TLE3 expression and poor prognosis of breast cancer in RFS, OS, and DMFS." (PMID 36451774, 2022).
breast carcinoma (continued). "Similarly, TLE3 was described as a co-repressor in breast cancer cells, where it co-regulates the expression of a subset of ERα target genes." (PMID 31855178, 2019). "Moreover, the interaction between TLE3 and FoxA1 was demonstrated in mouse liver cells and in our breast cancer cells." (PMID 25223786, 2014). "Moreover, a study in tamoxifen-resistant breast tumors showed that the expression of TLE3 was associated with longer remission periods, demonstrating a potential role for TLE3 in breast cancer progression." (PMID 25223786, 2014). "Here, we show that in breast cancer MCF-7 cells, TLE3, a co-repressor of the Groucho/Grg/TLE family, interacts with FoxA1 and is detected at regulatory elements of ERα target genes in absence of estrogen." (PMID 25223786, 2014). "Given that TLE3 interacts with FoxA1 and that both factors are important in cancer development, we investigated their role in the MCF-7 breast cancer cell line." (PMID 25223786, 2014). "Another study found that TLE3, a transcription corepressor recruited by FOXA2 to the ZEB2 promoter, inhibits the expression of the EMT-related transcription factor ZEB2, thereby suppressing the EMT of breast cancer cells." (PMID 36451774, 2022). "TLE3 expression is positively correlated with taxane sensitivity in patients with ovarian carcinoma but not breast cancer." (PMID 35832194, 2022). "In studies of ovarian and breast cancers, increased TLE3 expression was related to a higher response rate to taxane-based chemotherapy, but TLE3 expression showed no predictive value in treating breast cancer at an early stage." (PMID 36438567, 2022). "Indeed, the expression of TLE3 was stronger in ERα-positive breast cancer cell lines compared to ERα-negative cell lines." (PMID 25223786, 2014).
colorectal cancer (5 papers, 2017 to 2025). A primary or metastatic malignant neoplasm that affects the colon or rectum. "In colorectal cancer, RNF6 ubiquitinates and degrades the transcriptional TLE3 through Wnt/β-catenin pathway." (PMID 35369571, 2022). "Given that stabilized β-catenin promotes the E3 ligase activity of UBR5 toward TLE3, we asked whether we could detect UBR5-dependent Ub-TLE3 in the colorectal cancer cell line HCT116, whose Wnt pathway activity is elevated due to a Δ45 mutation in one of its β-catenin alleles." (PMID 28689657, 2017).
prostate carcinoma (5 papers, 2014 to 2023). A carcinoma that arises from epithelial cells of the prostate gland. "Together, our data shows that loss of TLE3 in conjunction with AR inhibition results in GR upregulation, leading to enzalutamide-resistance in LNCaP prostate cancer cells." (PMID 31855178, 2019). "In summary, we have identified TLE3 loss as a novel resistance mechanism to AR-targeted therapeutics in prostate cancer cells." (PMID 31855178, 2019). "In a genome-wide CRISPR-Cas9 screen using LNCaP prostate cancer cells, loss of co-repressor TLE3 conferred resistance to AR antagonists apalutamide and enzalutamide." (PMID 31855178, 2019). "In a prostate cancer study, TLE3 deficiency was linked to resistance to AR inhibitors." (PMID 36438567, 2022). "In prostate cancer, loss of TLE3 is associated with resistance to AR inhibitors." (PMID 36438567, 2022). "Further study revealed that the expression of the glucocorticoid receptor (GR) gene was depressed by AR and TLE3 in prostate cancer cells." (PMID 36438567, 2022). "Analysis of RNA expression in two prostate cancer patient cohorts, showed an inverse correlation between TLE3 and GR expression and worse prognosis of prostate cancer patients with low TLE3 expression treated with antihormonal therapy." (PMID 31855178, 2019). "Together, our results provide novel insights into the regulation of the GR locus in the context of AR inhibition in prostate cancer cells, implicating TLE3 as a regulator of GR-mediated enzalutamide resistance." (PMID 31855178, 2019). "(A–B) RNA-seq analysis showing the correlation between TLE3 and GR expression in tumor samples from prostate cancer patients." (PMID 31855178, 2019). "Combined, these data show that TLE3 and GR are inversely correlated in prostate cancer patient samples and that low TLE3 and high GR expression were observed in several cases of enzalutamide resistance." (PMID 31855178, 2019). "Here, we report an unexpected role for TLE3 in regulating AR-mediated repression of the GR locus affecting AR inhibitor sensitivity in prostate cancer cells." (PMID 31855178, 2019). "Through a genome-wide CRISPR-Cas9 screen we identified transducin-like enhancer of split 3 (TLE3) as a modulator of AR inhibitor sensitivity that, upon loss, confers resistance to enzalutamide in prostate cancer cells." (PMID 31855178, 2019). "Analysis of the TCGA prostate cancer patient dataset filtered for patients who had undergone anti-hormonal therapy revealed a correlation between TLE3 expression and biochemical recurrence (p = 0.033, n = 65)." (PMID 31855178, 2019). "We next investigated the effect of TLE3 expression levels on disease progression in prostate cancer patients." (PMID 31855178, 2019). "Together, our findings reveal a mechanistic link between TLE3 and GR-mediated resistance to AR inhibitors in human prostate cancer." (PMID 31855178, 2019). "As prostate cancer is considered a heterogenous disease, for which only a few cell lines are available of which a subset is AR-driven, we next tested whether drug resistance as a result of TLE3 loss could be confirmed in two other prostate cancer cell lines; CWR-R1 and LAPC4." (PMID 31855178, 2019). "TLE3 and GR expression in tumors of prostate cancer patients." (PMID 31855178, 2019). "Our data, implicating TLE3 in the regulation of GR expression and drug resistance, complements increasing evidence describing the role of this receptor in bypassing AR blockade in prostate cancer cells." (PMID 31855178, 2019). "(C) Kaplan-Meier curve showing the biochemical recurrence of prostate cancer patients from the TCGA dataset, only patients receiving anti-hormonal therapy were included (65 patients) using an optimal cut-off for high versus low TLE3 expression." (PMID 31855178, 2019). "Thus, our results warrant further investigation into the role of TLE3 and enzalutamide resistance in prostate cancer patients." (PMID 31855178, 2019).
prostate carcinoma (continued). "Moreover, TLE3 and AR binding at this region occurs at the same regulatory element described previously to be relevant in the regulation of GR in prostate cancer progression." (PMID 31855178, 2019). "Our finding that TLE3 loss, in conjunction with AR inhibition, leads to GR upregulation provides deeper insight into the epigenetic regulation of the GR locus in prostate cancer cells and supports the previously undescribed role of TLE3 in conferring enzalutamide sensitivity via GR." (PMID 31855178, 2019). "The availability of in vitro prostate cancer models is limited, and the heterogeneous nature of resistance mechanisms to antihormonal therapies in prostate cancer may explain why TLE3 loss did not confer resistance to enzalutamide in LAPC4 and CWR-R1 cells." (PMID 31855178, 2019). "The ubiquitin‒proteasome degradation system seems to play a critical role in regulating TLE3 levels; however, the mechanisms by which TLE5 is suppressed in metastatic colon and prostate cancers are not fully understood." (PMID 36438567, 2022). "In the absence of TLE3, further inhibition of AR led to the derepression of GR expression, which confers resistance to AR-targeted therapy in prostate cancer." (PMID 36438567, 2022).
ovarian carcinoma (4 papers, 2014 to 2023). A malignant neoplasm originating from the surface ovarian epithelium. "By contrast, the high-expressed mRNA level of TLE3 was connected with poor PFS (progress-free survival) of ovarian cancer, poor OS, FP, and PPS of gastric cancer, and poor RFS, PFS, and DSS of liver cancer." (PMID 36451774, 2022). "Moreover, patients with breast and ovarian cancers with high TLE3 expression were reported to respond well to a chemotherapeutic regimen that included taxane." (PMID 38203206, 2023).
melanoma (3 papers, 2019 to 2022). A malignant, usually aggressive tumor composed of atypical, neoplastic melanocytes. "Given that HDAC activity is associated with melanoma progression, we examined the relationship between TLE3, a TLE family member, and melanoma." (PMID 30719233, 2019). "TSA impaired the progression of xenograft tumors generated by B16 melanoma cell line subcutaneous injections in a similar manner as in vitro experiments mediated by Tle3 downregulation." (PMID 35409020, 2022). "TLE3 expression is also increased during melanoma progression, and overexpression of TLE3 promotes melanoma cell proliferation and tumor progression." (PMID 36438567, 2022). "Here, we examined the relationship between expression of TLE3 and malignant melanoma, as well as the effect of TLE3 on cell proliferation using melanoma cells." (PMID 30719233, 2019). "Overexpression of Tle3 in B16 murine melanoma cells led to an increase in cell proliferation (p < 0.01) as well as the number of cyclinD1-positive cells." (PMID 30719233, 2019). "Overexpression of Tle3 in B16 melanoma cells stimulated mRNA expression of cell cycle related genes such as CyclinD1,CyclinD2, and CyclinA2." (PMID 30719233, 2019). "We first examined the mRNA levels of TLE3 in human melanoma patients by analyzing an NCBI Gene Expression Omnibus (GEO) dataset of melanoma microarray profiles." (PMID 30719233, 2019). "In conclusion, these data indicate that Tle3 is required, at least in part, for proliferation in the B16 mouse melanoma model." (PMID 30719233, 2019). "In human HMV-II melanoma cells, siRNA knockdown of TLE3 expression resulted in a reduction of CYCLIN A2 protein levels." (PMID 30719233, 2019). "Our data not only shows an enrichment of TLE3 in melanoma, but also shows that knockdown of TLE3 can reduce cell proliferation and tumor growth thus identifying a potential therapeutic target." (PMID 30719233, 2019). "The expression of TLE3 was further increased in malignant samples compared to benign skin nevi, suggesting that the expression of TLE3 is involved in the progression of melanoma." (PMID 30719233, 2019). "In contrast, siRNA-mediated knockdown of Tle3 in B16 cells or TLE3 in HMV-II human melanoma cells decreased proliferation (p < 0.01)." (PMID 30719233, 2019). "Needless to say, it is important to examine the role of Tle3 not only in cell proliferation but also in cell apoptosis, invasion and distal metastasis to understand the full scope of melanoma especially in vivo." (PMID 30719233, 2019). "Further experiments are needed to elucidate the exact role of TLE3 in the pathophysiology of melanoma." (PMID 30719233, 2019). "Altogether, these data suggest that HDACs are required for the TLE3’s ability to increase proliferation of melanoma." (PMID 30719233, 2019). "Consistent with a role for TLE3 in melanoma development, our analysis of gene expression data from patient samples showed that TLE3 mRNA was highly enriched in tumor samples compared to normal skin or benign skin nevi samples." (PMID 30719233, 2019). "Notably, the protumorigenic activity of TLE3 in melanoma can be blocked by treatment with HDAC inhibitors." (PMID 36438567, 2022). "Given that TLE3/HDACs can inhibit Wnt/β-catenin signaling and that Wnt activation has adverse effects on the growth of melanoma cells, these results suggest that TLE3 might promote melanoma progression by regulating Wnt signaling." (PMID 36438567, 2022). "Immunofluorescence imaging revealed that TLE3 was also expressed in HMV-II human melanoma cells." (PMID 30719233, 2019). "Our data also demonstrates that Tle3 has a positive effect on the proliferation of melanoma cells." (PMID 30719233, 2019). "The mechanism by which TLE3 affects melanoma proliferation remains unknown although our data strongly suggests that it involves the modulation of HDAC activity." (PMID 30719233, 2019). "In conclusion, the reduction of TLE3 levels may provide a novel and beneficial method to control melanoma." (PMID 30719233, 2019).